CXCR4 (C-X-C motif chemokine receptor 4)
Diseases named in the same sentence as CXCR4 in open-access papers (continued):
Sharing a sentence is not in itself a finding about the gene and the disease.
glioma (continued). "Would halogenated cyclam derivatives, thought to be hydrophobic on structure-based estimates of their lipophilicity, provide new radiolabeled ligands for imaging CXCR4 expression in gliomas and PCNSL?" (PMID 32239371, 2020). "Transwell assay was performed to evaluate the regulation of miR-21 and CXCR4 on glioma cell invasiveness." (PMID 33123586, 2020). "Our data confirmed that the CXCR4 expression was upregulated in malignant glioma tissues and glioma cells in comparison to normal tissues or glial cells." (PMID 33123586, 2020). "We then performed ELISA analysis to determine the changes of glioma-secreting chemokine responding to the reductions of microglial CXCR4." (PMID 32194542, 2020). "It was also observed that CXCR4 is highly expressed in glioma progenitor cells, whereas its ligand CXCL12 promotes a specific proliferative response in these cells." (PMID 32456359, 2020). "Further, we examined the expression of miR-21 and CXCR4 in two invasive-prone glioma cell lines (U87 and U251) in comparison to a normal glial cell line (HAc)." (PMID 33123586, 2020). "Using cellular magnetic resonance imagining (MRI) to track the labeled stem cells, increased BM-MSC migration toward in vitro and in vivo glioma models was found, and the SDF-1/CXCR4 signaling axis was associated to this phenomenon." (PMID 33365304, 2020). "Inhibition of miR-21, CXCR4, and miR-21 and CXCR4 together all reduced the migration, invasiveness, proliferation, and enhanced apoptosis in glioma cells, as well as reduced tumor volume and mass in xenograft model." (PMID 33123586, 2020). "Anti-miR-21 + sh-CXCR4 almost abrogated the proliferation, cell invasion, and migration in migration-prone glioma cells." (PMID 33123586, 2020). "Herein, we investigated the combined effects of miR-21 and CXCR4 by lentiviral-mediated gene recombinant technology on glioma malignancy." (PMID 33123586, 2020). "A growing number of studies have found that CXCR4 is more likely present within the glioma stem like cell population compared with differentiated glioma cells." (PMID 31382985, 2019). "Flow cytometry analysis showed that the expression level of CXCR4 in EVs was higher in high-grade (III & IV) glioma patients than in low-grade (II) ones, although the difference was not statistically significant." (PMID 31410219, 2019). "They demonstrated specific increases in CD8+ T cell responses following NP treatment when membranes were derived from CXCR4-high U87 glioma cells." (PMID 34138027, 2019). "In glioma, the receptor, CXCR4, and its ligand, CXCL12, have been implicated in this mechanism in rat and patient glioma cells." (PMID 31632905, 2019). "We compared the expression of the interest pathway molecules in the cell lines and found that the expression of Notch1 signaling genes and CXCR4 was significantly higher in glioma stem like cells and neurospheres than in conventional cell lines." (PMID 31382985, 2019). "Subventricular zones (SVZs) of the brain accommodate neural stem cells and have been shown to attract human GBM stem(-like) cells through SDF-1/CXCR4 signaling in an orthotopic glioma mouse model." (PMID 30622535, 2018). "EPN cells also express low levels of CD133 (a glioma stem cell marker), nestin (a marker of immature neural stem cells), CXCR4 (CXC receptor 4, which is involved in tumor migration) and SSEA-3 (stage-specific embryonic antigen 3)." (PMID 29774098, 2018). "We previously showed using an agent based model that heterogeneous populations of glioma cells are exquisitely sensitive to small changes in CXCR4 and CXCL12 co-expressing cells, leading to enhanced flow response via this autologous chemotaxis mechanism." (PMID 30451884, 2018). "C-X-C chemokine receptors type 4 (CXCR4) have been reported to overexpress in most cancers, including glioma." (PMID 30233327, 2018).
glioma (continued). "Nonetheless, patient-derived glioma stem cells display heterogeneity in their dependence on CXCR4 versus other receptor-mediated responses to flow such as CD44 mechanotransduction." (PMID 30451884, 2018). "All these factors suggest that the downregulation of CXCR4 in persons with schizophrenia would be a protective aspect for reducing the incidence of glioma." (PMID 30233327, 2018). "In accordance with these observations, anti-angiogenic therapy of orthotopic mouse glioma promotes GBM invasion by CXCR4 upregulation." (PMID 30622535, 2018). "The results demonstrated that the expression ratios of ABCG2, CXCR4 and nestin were higher on glioma stem cells than on brain glioma cells." (PMID 28615716, 2017). "Here, we determined that the expression of MIF and CXCR4 was positively correlated with the grade of glioma and the HIF level." (PMID 29113309, 2017). "The CXCR4/CXCL12 molecular axis is involved in numerous responses that drive glioma progression, such as tumor cell proliferation, survival, angiogenesis, invasion and migration." (PMID 28423060, 2017). "Cell invasion analyses showed that D609 was able to induce a stronger inhibition of U87MG cell invasion (46%) compared with that induced by the conventional CXCR4 antagonist (38%), which proved to inhibit glioma cell motility." (PMID 28423060, 2017). "In glioma specimens, we found that VM formation was closely associated with high co-expression of MIF and CXCR4." (PMID 29113309, 2017). "The expression of HIF1α, MIF and CXCR4 in clinical specimens (six normal brain tissues and twenty-five human glioma tissues) was positively correlated with the grade of glioma." (PMID 29113309, 2017). "CXCR4 was newly acknowledged as stem cells surface marker in several of tumors (including glioma, pancreatic adenocarcinoma and synovial sarcoma)." (PMID 28076327, 2017). "Several reports demonstrated a correlation between high levels of CXCL12 and CXCR4 and tumor malignancy in different tumor types, including gliomas." (PMID 28423060, 2017). "One study used 68Ga-NOTA-NFB, a derivative of the peptide antagonist of CXCR4, T140, to image gliomas." (PMID 29088715, 2017). "In this study, we established a previously unrecognized link between VM formation and high co-expression of MIF and CXCR4 within hypoxic regions of glioma specimens." (PMID 29113309, 2017). "The results demonstrated that high-grade gliomas had more VM-positive specimens than did low-grade gliomas and that VM was closely associated with high co-expression of MIF and CXCR4 in gliomas." (PMID 29113309, 2017). "Numerous studies on preclinical glioma models have shown that the blockade of the CXCL12/CXCR4 axis by specific antagonists affects tumor growth, vasculogenesis and post-radiation recurrence." (PMID 28423060, 2017). "The expression of ATP-binding cassette subfamily G member 2 (ABCG2), chemokine receptor type 4 (CXCR4) and nestin were identified on human brain glioma cells and glioma stem cells (GSCs)." (PMID 28615716, 2017). "We used immunohistochemistry to evaluate the expression of HIF1α, MIF and CXCR4 in our glioma specimens." (PMID 29113309, 2017). "Activation of CXCR4 also promotes the growth and production of angiogenetic factors by glioma stem cells." (PMID 27007162, 2016). "AMD3100 mediated blockade of CXCR4 in U-118 glioma cells inhibiting their migration, chemotactic ability, and survival, albeit in-vitro." (PMID 27863376, 2016). "Down regulating CXCR4 expression or blocking this receptor is a powerful mechanism for achieving anti-glioma resistance, further making the therapeutic effects of radiotherapy more evident." (PMID 27863376, 2016). "Conversely, CXCR4 inhibition reduced homing of endothelial progenitor cells to the tumor in a murine glioma model." (PMID 27835905, 2016). "Consistently, post-radiation therapy inhibition of CXCL12/CXCR4 interaction resulted in the inhibition of tumor recurrence in glioma models." (PMID 27015814, 2016).
glioma (continued). "Using this approach, we intended to specifically determine the role of CXCR4 in tumor migration and invasion of mouse glioma GL26-Cit cells towards endothelial cells." (PMID 27863376, 2016). "It was shown that CXCR7 was found on “differentiated” glioma cells, which mediated their resistance to apoptosis, whereas CXCR4 is expressed in GSCs." (PMID 26880981, 2016). "A variety of classic pro-angiogenic factors, including VEGF, HIF-1, and CXCR4, have been reported to be regulators for the formation of glioma neovessels." (PMID 26515590, 2016). "We investigated the in-vivo role of CXCR4 in perivascular invasion of glioma cells using shRNA-mediated knock down of CXCR4." (PMID 27863376, 2016). "A phase I study of the CXCR4 inhibitor plerixafor and bevacizumab is ongoing for patients with recurrent high-grade gliomas (NCT01339039)." (PMID 26920352, 2016). "Our data show that inhibiting CXCR4 in glioma cells reduces the migration and invasion ability of mouse glioma GL26-Cit in-vitro and in-vivo." (PMID 27863376, 2016). "Since CXCL12 can increase tumor cell survival, knocking down CXCR4 would lead to an increase in glioma cell death." (PMID 27863376, 2016). "Previous studies have also shown that human breast cancer cell lines exhibit increased invasion in the direction of IFF via a CCR7-dependent mechanism, while glioma cell invasion can occur through CXCR4-dependent autologous chemotaxis." (PMID 26560447, 2015). "For example, activation of CXCR4 induces leukemia cell trafficking and homing to the bone marrow and is critical for the growth of both malignant neuronal and glial tumors." (PMID 26347749, 2015). "Further analysis using STRING identified four main gene networks (IL-6, BCL2, PTGS2 and CXCR4) that were downregulated in glioma cells silenced for RTVP-1." (PMID 26267319, 2015). "In previous studies, we demonstrated that TMP exerts potent inhibitory effects on neovascularization, suppresses the tumorigenic behavior of glioma cells, and protects neural cells by regulating CXCR4 expression." (PMID 26275042, 2015). "CXCL12/SDF-1 and its receptor CXCR4 have been shown to promote glioma stem cell-mediated VEGF production and tumour angiogenesis via PI3K/AKT signalling." (PMID 24971349, 2014). "In these perinecrotic areas (“pseudopalisading” necrosis), characterized by high cellularity due to the powerful invasion of glioma cells, CXCR4 and CXCL12 co-localize in the same tumor cells." (PMID 24904289, 2014). "This is exemplified by observations in human glioma in which CXCR4/CXCL12 interaction favors an autocrine or paracrine loop for tumor cell proliferation." (PMID 25110692, 2014). "Conversely, the glioma onco-suppressive gene LRRC4 inhibits CXCL12/CXCR4-induced cell proliferation, chemotaxis and invasiveness reducing ERK1/2 and Akt signaling." (PMID 24904289, 2014). "In previous studies, we first demonstrated that TMP protects cerebral neurocytes and inhibits glioma cells by down-regulating the expression of the chemokine receptor CXCR4." (PMID 24505417, 2014). "CXCR4/CXCL12 growth stimulating effects were also detected in glioma stem cells via an AKT-mediated prosurvival and self-renewal pathway." (PMID 25110692, 2014). "In a previous study we showed that TMP-mediated glioma suppression and neural protection involves the inhibition of CXCR4 expression." (PMID 24505417, 2014). "Although the key role of CXCR4 in mediating SDF-1α-induced migration of glioma cells is well established, that of CXCR7, to our knowledge, has still not been confirmed." (PMID 23865743, 2013). "We transfected LN229 and LN308 glioma cells with HA-tagged CXCR4 (CXCR4-HA) or an empty vector as control." (PMID 23865743, 2013). "Our previous data showed that CXCR4 inhibition by AMD3100 decreased the levels of SDF-1α-induced phosphorylation of FAK in LN308 glioma cells." (PMID 23865743, 2013). "We have previously shown that AMD3100, a CXCR4 inhibitor, decreases glioma cell migration towards SDF-1α." (PMID 23865743, 2013).
glioma (continued). "In LN229 and LN308 glioma cells, both inhibition of CXCR4 by AMD3100 and shRNA-mediated knockdown of CXCR7 expression diminished migration towards SDF-1α and reduced levels of SDF-1α-induced phosphorylation of ERK1/2 and Akt." (PMID 23865743, 2013). "It is probable that CXCR7 is part of a functional heterodimer, together with CXCR4, which mediates the migration of glioma cells towards SDF-1α under hypoxic conditions." (PMID 23865743, 2013). "Blocking the interaction of SDF-1 and its receptor CXCR4, by using the CXCR4 inhibitor AMD3100 or a CXCR4 neutralizing antibody, resulted in decreased tumor perfusion and an enhanced radioresponse of the glioma xenograft model." (PMID 23882218, 2013). "We previously provided evidence that SDF-1α induces phosphorylation of ERK1/2, Akt and FAK in LN308 glioma cells that display CXCR4-mediated migration towards SDF-1α." (PMID 23865743, 2013). "It is also known that CXCR4 expression and CXCR4 phosphorylation levels correlate with glioma severity." (PMID 24023874, 2013). "Because SDF-1 and its receptor CXCR4 are involved in glioma invasion, we performed immunostaining for this ligand-receptor pair." (PMID 22539956, 2012). "Stromal cell-derived factor-1 and its receptor CXCR4 were highly expressed in and around glioma xenografts, suggesting their role in glioma progression and invasion." (PMID 22539956, 2012). "The so called vascular modulatory cells of the myeloid lineage (CD11b+CD45+) have been shown to be recruited to glioma via the SDF-1/CXCR4 axes upon the hypoxic up-regulation of SDF-1 and HIF-1α in tumors." (PMID 24213237, 2012). "Similar results were obtained when CXCR4 was specifically blocked on the MC surface and cells were allowed to migrate towards glioma-conditioned medium." (PMID 21949886, 2011). "Further, mimicking the situation in the mouse gliomas, tryptase-positive MCs present in human GBMs were frequently positive for CXCR4." (PMID 21949886, 2011). "Further, human and mouse glioma MCs were strongly positive for its cognate receptor CXCR4, this being in agreement with previous reports showing the expression of CXCR4 in human glioma." (PMID 21949886, 2011). "In agreement with a role of the CXCL12/CXCR4 axis in promoting MC migration into the tumors, mMCP-6 positive MCs in both Ntv-a Arf−/− and Gtv-a Arf−/− mouse gliomas were frequently (with an average of 90%) CXCR4 positive." (PMID 21949886, 2011). "Flow cytometry was used to determine transduction efficiencies in NP2/CD4/CXCR4 (glioma cell line stably transduced with the HIV receptors) and HeLa/CD4 cell lines." (PMID 20929586, 2010). "This clone demonstrated robust viral propagation and profound syncytium formation in CD4+, CXCR4-expressing human glioma NP-2 cells, indicating that p05MYKL045.1 is a CXCR4-using virus." (PMID 19688091, 2009). "Several other studies on breast, lung, pancreatic, prostate and thyroid cancer, and glioma suggested a role of CXCR4 in the metastasatic process." (PMID 15978137, 2005). "However, recent advances in radiolabeled nanoparticles and CXCR4-targeted imaging agents already under evaluation in adult gliomas suggest promising avenues for precise, low-toxicity diagnosis and therapy in pediatric neuro-oncology." (PMID 40806525, 2025). "CXCR4-overexpressing cells achieved complete remission in several treated animals and prolonged survival compared to controls, highlighting this receptor’s critical role in navigating the glioma chemokine landscape." (PMID 40895575, 2025). "Then, we compared the expression of PD-L1 and CXCR4 mRNA in glioma and normal brain." (PMID 38164271, 2024). "The results showed that PD-L1 and CXCR4 highly expressed in glioma." (PMID 38164271, 2024). "Then, we used WB to examine whether IGFBP5 inhibition or overexpression could mediated PD-L1 and CXCR4 expression in glioma cells." (PMID 38164271, 2024).
glioma (continued). "Moreover, our study further demonstrates IGFBP5 participates in proliferation and invasion involved in EMT and Hippo-YAP signaling pathway in glioma cells, and influences the expression of PD-L1 and CXCR4 expression." (PMID 38164271, 2024). "The results indicate that the microglia may be involved in the treatment of central nervous system cancer pain mediated by CXCL12/CXCR4." (PMID 39641645, 2024). "In the orthotopic model, CXCR4 antagonism by POL5551 combined with the anti-VEGF antibody B20-4.1.1 decreased glioma invasiveness and vascular density, resulting in a valuable strategy to overcome antiangiogenic therapy resistance, as revealed by both in vitro and in vivo experiments." (PMID 36980182, 2023). "In recent decades, CXCR4 has been increasingly studied in glioma." (PMID 37626511, 2023). "CXCR4-directed anti-glioma therapy using cytotoxic radionuclides like 177Lu may thus be a promising therapy for glioblastoma." (PMID 37835806, 2023). "Additionally, glioma cells expressing higher levels of CXCR4 formed more rapidly growing and lethal tumors in nude mice." (PMID 39355049, 2023). "Additionally, the knockdown of CXCR-4 in mouse glioma cells inhibits the in vitro migration towards MBVE cells, decreasing perivascular invasion." (PMID 37108208, 2023). "Additionally, the intracranial inoculation of CXCR-4 knockdown glioma cells reduced tumor growth and perivascular invasion, resulting in more sensitivity to radiotherapy, leading to increased survival." (PMID 37108208, 2023). "CXCR4/CXCL12 signaling promoted tropism of NSCs toward glioma cells." (PMID 37693056, 2023). "A poorer prognosis was observed after surgery in patients with CXCR4-positive gliomas." (PMID 39355049, 2023). "In a syngeneic murine glioma model, both the number of Tregs and the expression of CXCR4 showed time-dependent upregulation, which may be one of the reasons for immune escape of glioma cells." (PMID 37790751, 2023). "Therefore, a pilot phase I/II trial (NCT01977677) studied the side effects and best dose of Plerixafor (a CXCR4 inhibitor) after radiation therapy plus TMZ to see how well it works in treating patients with newly diagnosed high-grade glioma." (PMID 35967394, 2022). "The effect of circFGFR1 on glioma malignancy is abolished in CXCR4 knockout cells." (PMID 35059468, 2022). "The CXCL12/CXCR4 axis drives cell proliferation, angiogenesis, and glioma invasion." (PMID 34687436, 2022). "Furthermore, CXCR4 level in glioma cells is positively correlated with circFGFR1 level, and higher CXCR4 expression is found in circFGFR1 overexpression groups." (PMID 35059468, 2022). "Compared to non-invasive tumor cells, gliomas have higher expression of CXCR4." (PMID 35204054, 2022). "In order to further confirm whether CXCR4 is responsible for the circFGFR1-induced glioma growth change, we generated a CXCR4 knockout SNB19 cell line by using CRISPR/Cas9 with a ribonucleoprotein (RNP) system." (PMID 35059468, 2022). "It is demonstrated that the endogenous stem cell factor (SCF) largely contributes not only to the expansion of the glioma-associated MCs but also to the localization of the MCs in the vicinity of the tumor blood vessel and glioma cells along with the CXCL12/CXCR4 axis." (PMID 34671362, 2021). "Here, we also show that astrocytes exposed to hypoxia upregulate the gene and protein expression levels of VEGF-A, which, once secreted to the microenvironment, can increase the invasion of glioma cells by activating C-X-C chemokine receptor type 4 (CXCR4) signaling." (PMID 33802060, 2021). "Furthermore, hepatocyte growth factor (HGF) upregulated chemokine receptor CXCR4 expression via NF-κB activation, leading to glioma cell (U87MG and LN 229) invasion." (PMID 34439380, 2021). "Thus, our results demonstrated that anti-miR-21 + sh-CXCR4 had an enhanced effect on both suppressing glioma cell proliferation and proapoptosis." (PMID 33123586, 2020).